ALB (albumin)
Diseases named in the same sentence as ALB in open-access papers (continued):
Sharing a sentence is not in itself a finding about the gene and the disease.
diabetes (continued). "Thus, diabetes and sarcopenia may be important factors associated with urinary albumin level." (PMID 31828155, 2019). "Statement: Measurement of urine albumin is recommended in patients with diabetes mellitus since it is essential for the early diagnosis of diabetic nephropathy." (PMID 30506489, 2019). "A glycated protein is considered by the immunological system as an “undesired” species, and consequently its enzymatic digestion is activated e.g. glycated albumin in diabetes." (PMID 30948622, 2019). "Following treatment with STZ, we found that KLF10 depletion significantly protected mice against diabetes‐induced proteinuria (urinary excretion of total protein and albumin), glomerular cell apoptosis, GBM thickening, and even renal fibrosis (and EV3)." (PMID 30948420, 2019). "Goodness of fit, discrimination, and calibration were worse for a simple model including age, sex, and eGFR than for a complicated model (plus albuminuria, systolic blood pressure, diabetes, serum albumin, and hemoglobin)." (PMID 30069609, 2019). "These factors remained significant even after adjustment for other factors: diuretic use, diabetes, proteinuria before admission, 24-hour systolic blood pressure, serum albumin, and serum creatinine (Model 2 and Model 3)." (PMID 31217504, 2019). "Previous studies involving patients with diabetes have indicated that sarcopenia is related to urinary albumin level, urinary protein level, and/or decreased eGFR." (PMID 31828155, 2019). "In the present study, the results showed that the combination of sex, age, serum creatinine, blood urea nitrogen, serum albumin, haemoglobin, serum phosphorus, diabetes mellitus, and heart failure as equation variables resulted in the best accuracy." (PMID 30971708, 2019). "Diabetes was associated with renal decline, as demonstrated by an increased serum creatinine, serum BUN and urine albumin‐to‐creatinine ratio." (PMID 30955247, 2019). "Selected variables included age, sex, employment status, income, education level, nutritional factor (high-sensitivity C-reactive protein and albumin), diabetes mellitus, severe anemia, basal serum creatinine, and proteinuria." (PMID 31863079, 2019). "Hypertension during pregnancy remained significantly associated with CAC even with additional adjustment for serum creatinine levels, urinary albumin creatinine ratio, menopause status, diabetes status and antihypertensive medication use." (PMID 31803759, 2019). "Old age, diabetes, and low baseline serum albumin are predictive factors for poorprognosis in PD patients." (PMID 30916219, 2019). "All included the variables of age, sex, eGFR, and urine albumin-to-creatinine ratio (ACR) (4-variable), with the addition of diabetes mellitus and hypertension (6-variable) or serum albumin, bicarbonate, calcium, and phosphate (8-variable)." (PMID 31693662, 2019). "In the analysis of predictors of CV mortality, moderate and severe calcification were independent predictors after adjusting for age, diabetes, ALB, LDL-C, and history of cerebrovascular disease." (PMID 31791277, 2019). "When levels of FFAs are elevated, such as during intense exercise, fasting or pathological conditions such as diabetes, albumin can bind in excess of 6 mol." (PMID 30266430, 2019). "In group A, male patients had higher levels of hemoglobin, serum albumin, creatinine, uric acid and also had higher percentage of diabetes than females, respectively (p < .05)." (PMID 31814501, 2019). "Factors significantly associated with HRQOL include presence of CVD, number of co-morbidities, haemoglobin, wheelchair-bound, age, diabetes mellitus and serum albumin." (PMID 31039745, 2019). "Multiple linear regression showed that STB was associated with haemoglobin concentration, platelet count, and serum triglyceride concentration in NDM and PDM patients, and with serum albumin, duration of diabetes, and smoking in PDM patients." (PMID 31427625, 2019).
diabetes (continued). "In the univariable analysis, increased cardiovascular mortality was associated with increased age, E/Ea, and E/LA strain, the presence of diabetes and coronary artery disease, and decreased albumin, LVEF, and LA strain." (PMID 31905735, 2019). "Our study suggests that prevented CKD progression and strictly cirrhosis treatment (albumin, ascites, hepatic encephalopathy, and coagulopathy correction) are important for managing cirrhosis, and perhaps more importantly, before diabetes development." (PMID 29416767, 2018). "In multivariable analysis, HOP remained significant after adjusting for log (BNP), age, sex, left ventricular ejection fraction, functional class, HF stage, diabetes mellitus, chronic kidney disease, hypertension, hemoglobin, and albumin." (PMID 30405858, 2018). "WT diabetic mice treated with rAAV-HSA displayed significant albuminuria at week 12 post-induction of diabetes and this was attenuated in WT mice treated with rAAV-esRAGE." (PMID 29844451, 2018). "Diabetes as a basal kidney disease, past CVD history, and lower serum albumin had positive associations with mortality; however, their risks were not significant." (PMID 30148875, 2018). "Burnt-out diabetes was reported in 20.7% and 5.4% of Japanese diabetic patients undergoing HD by using glycated hemoglobin and glycated albumin, respectively." (PMID 30314341, 2018). "For the total sample of men, these biomarkers include low serum magnesium and albumin, and presence of diabetes." (PMID 29806859, 2018). "Diabetes is responsible for reducing blood levels of albumin, which is also indicative of liver failure." (PMID 30333575, 2018). "eGFR = estimated glomerular filtration rate; ACR = albumin creatinine ratio, DM = diabetes mellitus, IHD = ischaemic heart disease, PVD = perivascular disease, CRP = c-reactive protein, uLG1M = urinary LG1M/Creatinine." (PMID 30273365, 2018). "Among the total anuric PD patients, non-survived patients showed a significantly older age, higher incidence of diabetes, coronary artery disease, and arrhythmia, and lower serum creatinine and albumin." (PMID 29694445, 2018). "In humans, dipyridamole monotherapy reduced urinary albumin excretion in diabetes patients with normo- or microalbuminuria." (PMID 29435184, 2018). "Urinary albumin excretion is an early sign of diabetic kidney disease, affecting every third individual with diabetes." (PMID 30120300, 2018). "There were two donors with diabetes with hemoglobin A1c levels higher than 6.5%, urine albumin excretion rate of more than 30 mg/day, or a history of treatment with insulin." (PMID 29027035, 2018). "A study on diabetic rats have observed that basement membrane thickness and permeability to serum albumin increased were significantly enhanced when diabetes coexisted with hypertension." (PMID 30302129, 2018). "MCP-l levels in peripheral blood of diabetes mellitus patients were positively correlated with urinary albumin excretion rate, and MCP-l mRNA and protein levels are higher in DN than in normal renal tissue." (PMID 30147653, 2018). "The prevalence of Hispanic ethnicity, history of diabetes, and high urine albumin levels at baseline were greater among persons with hematuria." (PMID 29940877, 2018). "In univariate analysis, associates of composite events included HOP, log (BNP), age, sex, left ventricular ejection fraction, functional class, HF stage, diabetes mellitus, chronic kidney disease, hypertension, hemoglobin, and albumin." (PMID 30405858, 2018). "Patients with diabetes were visited 2–4 times every year with regular assessment of glycated hemoglobin (HbA1c), urinary albumin excretion (UAE), and ophthalmoscopy." (PMID 29853876, 2018). "For example, low levels of serum albumin and magnesium, as well as presence of diabetes, were significantly more prevalent for men in the lower, compared to the upper HS tertile, while only the presence of diabetes was significant for women." (PMID 29806859, 2018).
diabetes (continued). "This highlights the need of incorporating routine urine albumin tests into the management program of persons with diabetes for early detection of CKD." (PMID 30279452, 2018). "In subjects with diabetes, only long sleepers had significantly increased urinary albumin excretion compared to intermediate sleepers." (PMID 29470498, 2018). "Patients with worse renal function were older, more commonly white, had a higher prevalence of hypertension, diabetes, coronary artery disease, or heart failure, higher urine albumin to creatinine ratios, and higher potassium and phosphorus levels." (PMID 29996910, 2018). "ANGPTL8 levels were positively correlated with triglycerides, duration of diabetes, and urine albumin-to-creatinine ratio (ACR) and negatively correlated with estimated glomerular filtration rate in type 2 diabetic patients with A2 and A3 (all P < 0.05)." (PMID 30072957, 2018). "Particularly important in diabetes is the decrease in the antioxidant capacity of human serum albumin (HSA) the main constituent protein of blood plasma." (PMID 30241420, 2018). "Diabetic kidney disease (DKD) is a common and serious microvascular complication of diabetes mellitus (DM), which is characterized by an elevated urinary albumin excretion rate, elevated blood pressure, and declined renal function." (PMID 29862302, 2018). "Individuals with hematuria were more likely to be Hispanic (22% vs. 9.5%, respectively), have diabetes (56% vs. 48%), lower mean eGFR (40.2 vs. 45.3 ml/min/1.73 m2), and higher levels of urinary albumin > 1.0 g/day (36% vs. 10%)." (PMID 29940877, 2018). "In contrast to the upregulation of DPP-4 expression observed in renal tissues injured by diabetes, obesity, and free fatty acid-bound albumin, the present study showed that DPP-4 expression was downregulated in rat renal tissues injected with MCT." (PMID 29607314, 2018). "Evidence of CKD (any stage) at the time of diabetes diagnosis was determined using eGFR and urine-albumin-creatinine ratios, the odds of which were assessed using logistic regression controlling for patient characteristics." (PMID 29425235, 2018). "Age, CVD history, diabetes, hemoglobin, albumin and C-reactive protein were found as common predictors in both our studies." (PMID 29066841, 2017). "Compared with patients with high pre-albumin level, patients with low pre-albumin level were more likely to have older age, higher tumor stage, higher rate of diabetes, regional lymph node metastasis and lymphovascular invasion." (PMID 27906675, 2017). "Predictors of SCD in AF included higher age, body mass index (BMI), coronary heart disease, hypertension, diabetes, current smoker, left ventricular hypertrophy, increased heart rate, and decreased albumin." (PMID 29117224, 2017). "Urine analysis of the STZ-induced diabetes rats showed significant increase in albumin level in the positive control group and decreased urinary creatinine level in G2 after 4 weeks." (PMID 28298934, 2017). "A total of 50 sera of diabetes patients were diluted 1:100 and tested for binding to native albumin and Amadori-albumin modified with different concentrations of glucose." (PMID 28192530, 2017). "After adjusting for duration of diabetes, BMI, TG, Albumin, Haemoglobin and WHR, the ORs for the prevalence of DN decreased significantly with the quartiles of bilirubin concentrations (P for the trend = 0.04)." (PMID 28363276, 2017). "After adjusting for multiple covariates, including age, diabetes, hypertension, cardiovascular disease, hemoglobin, serum albumin, and total cholesterol, BHD activity was significantly associated with the risk of CKD." (PMID 28228118, 2017). "Commercial assays that measure glycated serum proteins (fructosamine) or glycated serum albumin can accurately reflect glycemic control of patients with diabetes with Hb Himeji." (PMID 28743307, 2017).
diabetes (continued). "A multivariable model, adjusted for demographics, comorbidity score, obesity, diabetes, CVD, RKF, albumin, creatinine, and phosphate, changed risk-ratio estimates only slightly." (PMID 28178126, 2017). "Inducing diabetes led to albuminuria, reflected by an albumin:creatinine ratio of 8.53 ± 2.59 mg/mmol, which was significantly higher than in control mice (3.06 ± 0.98 μg/mg; p < 0.001)." (PMID 28620823, 2017). "We included 17 candidate predictors in our initial model, and the final model ultimately contained only six variables: age, diabetes mellitus status, history of CV events, dialysis time per session, phosphorus level, and albumin level." (PMID 28273175, 2017). "CHD was the strongest predictor (>3-fold risk), followed by diabetes and LVH (>2-fold risk), and then higher age, increased BMI, hypertension, smoking, increased heart rate, and low albumin (<2-fold risk)." (PMID 29117224, 2017). "Diabetes sera showed less or moderate binding with Amadori-albumin modified with 5, 25, 50 mM glucose." (PMID 28192530, 2017). "The process of albumin glycation influences the pharmacokinetics of drugs, thus monitored pharmacotherapy is reasonable in the case of diabetes and hypertension polypharmacy." (PMID 29258218, 2017). "Renal function was not different between the groups, though urinary ACR was higher in those with diabetes and serum albumin levels were lower in T2DM+ than in C+." (PMID 28320782, 2017). "Development of diabetes was followed by measurements of blood glucose and urine albumin-to-creatinine ratio." (PMID 28751823, 2017). "In the current analysis of BDI scores, serum levels of albumin, C-peptide, chronic hepatitis C infection, diabetes, and ABI were all demonstrated to be correlated with symptoms of depression in patients on MHD." (PMID 28455662, 2017). "We used data from 1381 newly diagnosed diabetes patients, and urinary albumin and 8-oxoGuo were assessed in morning urine collected at the time of diabetes diagnosis and at a follow-up visit 6 years later." (PMID 28666207, 2017). "In hemodialysis patients with type 2 DM, diabetes duration and serum glycated albumin, a marker of glycemic control in patients receiving hemodialysis, were 22.9 ± 12.8 years, and 20.1 ± 4.73%, respectively." (PMID 29133805, 2017). "It is thus likely that a lower albumin level promotes diabetes-induced muscle weakness, followed by cytokine-induced impairment of insulin secretion in pancreas, and elevation of circulating glucose levels." (PMID 28360943, 2017). "The final prediction model contained six variables: age, diabetes status, history of CV events, dialysis time per session, and serum phosphorus and albumin levels." (PMID 28273175, 2017). "The main outcome measures were estimated CKD prevalence (by serum creatinine-based estimated glomerular filtration rate (eGFR) and dipstick urine albumin); and estimated prevalence of CKD risk factors (diabetes, hypertension and obesity)." (PMID 28056873, 2017). "Comorbidities included hypoalbuminemia (albumin < 35 g/L) (83.3%), diabetes mellitus (22.2%), coronary artery disease (5.6%), chronic obstructive pulmonary disease (5.6%), chronic renal failure requiring dialysis (5.6%), and immunocompromised state (5.6%)." (PMID 29057121, 2017). "Information on covariates was complete for all patients, except for some missing values on diabetes (3.5% missing) and albumin (1.2% missing)." (PMID 28679361, 2017). "We used a LASSO Cox regression model to build the final prediction model, which selected seven variables from candidate variables in the training set: age, CVD, diabetes, albumin, hemoglobin, Hs-CRP, and 24-hours urine output." (PMID 29066841, 2017). "These risk factors include mainly age, gender, BMI, HbA1c, diabetes duration, blood pressure, lipids, brain natriuretic peptide (BNP), and albumin." (PMID 28348587, 2017).
diabetes (continued). "32% diabetes patient’s sera showed appreciably high binding with Amadori-albumin modified with 75mM glucose compared to the native albumin." (PMID 28192530, 2017). "Microalbuminuria, defined as an urinary albumin excretion rate between 30 and 300 mg/day, strongly predicts the development of nephropathy in diabetes mellitus." (PMID 28662169, 2017). "Of those with urine testing in Nevis (n = 929), 13.5% had urine albumin ≥30 mg/dL, and diabetes was an independent predictor of this finding (OR = 2.43, 95% CI 1.53–3.87)." (PMID 28056873, 2017). "In the present study, we induced diabetes in MBL knockout mice and in wild type C57BL/6J mice by low-dose streptozotocin injection and measured blood glucose and urine albumin-to-creatinine ratio to monitor development of diabetes." (PMID 28349070, 2017). "Diabetes, hypertension, low albumin levels, elevated international normalized ratio, and dirty/infected wound classification were only significant in univariable analysis." (PMID 29255536, 2017). "Recently, a novel research study detected kidney damage in patients with type 2 diabetes mellitus by comparing the microalbumin/creatinine ratio with 24-hour urinary albumin content." (PMID 28299325, 2017). "When results indicated diabetes, a test for kidney damage was offered (urinary albumin-to-creatinine ratio)." (PMID 28660184, 2017). "Definition of factors, existence of diabetes mellitus, age 2 50 years, IL-18 2 804.3 pg/ml, IL-6 2 3.92 pg/ml, IL-1B 2 0.86 pg/ml, and averaging albumin level < 3.8 gm/dl within the first year of PD." (PMID 28474577, 2017). "This suggests a role of Amadori-albumin (in chronic condition of hyperglycaemia) in the development and progression of diabetes and related complications." (PMID 28192530, 2017). "Overall, participants from low to high quartiles of GGT or SF tended to be older, obese, with high levels of triglyceride, MDA, urinary albumin, and high incidences of diabetes mellitus, hypertension, and metabolic syndrome." (PMID 28659657, 2017). "Both groups had preserved renal function with eGFR more than 60 ml·min−1·1.73 m−2, though urinary albumin/creatinine ratio (ACR) was higher in patients with diabetes and serum albumin was slightly lower." (PMID 28320782, 2017). "Telmisartan was useful for decreasing systemic inflammation and levels of urinary albumin excretion in patients who had type 2 diabetes mellitus and had undergone coronary artery bypass surgery." (PMID 27834982, 2017). "The STZ-model of type 1 diabetes was further validated by the diabetes-induced kidney hypertrophy and albumin excretion found in treated C57BL/6J mice." (PMID 28349070, 2017). "We further examined the effect of serum albumin on progression to overt diabetes in subjects who developed prediabetes." (PMID 28430803, 2017). "Other factors: Gender, octreotide therapy, history of diabetes, and preoperative serum albumin levels were respectively reported in 16, 5, 9, 3 enrolled studies." (PMID 28298641, 2017). "Diabetes mellitus, age ≧ 50 years, IL-18 ≧ 804.3 pg/ml, IL-6 ≧ 3.92 pg/ml, IL-1ß ≧ 0.86 pg/ml, and average levels of albumin <3.8 gm/dl." (PMID 28474577, 2017). "Several risk factors of microvascular complications have been reported in adults with T2DM, such as duration of diabetes, age, blood pressure, fasting plasma glucose, urinary albumin excretion levels, and elevated C-Reactive Protein levels." (PMID 28854950, 2017). "Here we confirmed the BRB breakdown in this diabetes model by showing that retinal accumulation of Evans blue-stained albumin doubled at 4 weeks after streptozotocin injection." (PMID 29026201, 2017). "If an older adult who has diabetes as well as albumin < 3.5 g/dL, the HR would be increased by 3.64 fold." (PMID 28978911, 2017). "Among 4,398 subjects who developed prediabetes, 3,851 subjects had a final serum albumin level that was measured at final follow-up or at the time of diabetes diagnosis." (PMID 28430803, 2017).